GPR149 (G protein-coupled receptor 149)
Description:
Orphan receptor.
Synonyms: PGR10; IEDA; R35
Tractability: Small molecule: it belongs to a druggable protein family. Antibody: UniProt places it where antibodies can reach, with medium confidence; UniProt predicts a signal peptide or a membrane-spanning region; its Gene Ontology location is reachable by antibodies, with medium confidence.
Target class: Family A G protein-coupled receptor; Membrane receptor
Gene: Protein-coding gene on chromosome 3 (154,334,943 to 154,430,190, reverse strand). Ensembl gene ENSG00000174948.
Subcellular location: Cell membrane
Gene Ontology:
Molecular function: G protein-coupled receptor activity; neuropeptide binding
Biological process: neuropeptide signaling pathway
Cellular component: neuron projection; plasma membrane; membrane
Genetic constraint (gnomAD): Loss-of-function variants: 51 observed, 50.12 expected, observed/expected ratio (o/e) 1.02, 90% interval 0.81 to 1.28. The upper end of that interval is the gene's LOEUF score, 1.28, which puts it in group 5 of 6, group 1 being the genes least tolerant of losing a copy. Missense variants: 947 observed, 921.9 expected, observed/expected ratio (o/e) 1.03, 90% interval 0.97 to 1.08. Synonymous variants: 396 observed, 372.25 expected, observed/expected ratio (o/e) 1.06, 90% interval 0.98 to 1.16.
Homologues: Orthologues: chimpanzee GPR149 (99% identical), macaque GPR149 (96% identical), pig GPR149 (88% identical), guinea pig GPR149 (82% identical), dog GPR149 (80% identical), mouse Gpr149 (79% identical), rat Gpr149 (79% identical), Drosophila melanogaster Rh7 (10% identical), Caenorhabditis elegans trhr-1 (8% identical). Paralogues in human: SSTR4 (11% identical), OPRK1 (11% identical), SSTR1 (10% identical), SSTR2 (10% identical), SSTR3 (10% identical), OPRD1 (10% identical), SSTR5 (10% identical), OPRM1 (10% identical), PTGDR2 (9% identical), NPBWR2 (8% identical), LTB4R2 (8% identical), OPRL1 (8% identical), and 5 more.
Diseases named in the same sentence as GPR149 in open-access papers:
GPR149 is named in the same sentence as 7 diseases in open-access papers, as found by Europe PMC text mining. Sharing a sentence is not in itself a finding about the gene and the disease. The quoted sentences say what the papers report.
demyelinating disease (2 papers, 2023 to 2024). A broad group of disorders that affect the myelin sheaths that cover the neurons. "Blocking GPR149 may even promote myelin repair in demyelinating diseases." (PMID 37887305, 2023).
coronary artery disease (1 paper, 2022). "Variants in the GPR149 gene, which encodes a seven-transmembrane G protein-coupled receptor (GPCR) class A family member, have been associated with coronary artery disease, HDL cholesterol level, and apolipoprotein A1 level." (PMID 35869121, 2022).
diabetes (1 paper, 2024). "However, given how widely Gpr149 is expressed in the brain, we propose that the importance of GPR149 extends beyond the field of obesity and diabetes research." (PMID 38282864, 2024).
migraine disorder (1 paper, 2023). A common, severe type of vascular headache often associated with increased sympathetic activity, resulting in nausea, vomiting, and light sensitivity. "Gene variants of GPR149 have also been reported in studies investigating migraine disorder susceptibility." (PMID 37887305, 2023).
Obesity (1 paper, 2024). Accumulation of substantial excess body fat. "When switched to HFD (60% fat), diet-induced obesity was significantly less pronounced in Gpr149−/− mice." (PMID 38282864, 2024). "While our data indicate a physiological role of GPR149 signaling in the context of diet-induced obesity and glucose homeostasis, additional studies are needed to understand the exact mechanisms linking GPR149 and the neural control of energy balance in both males and females." (PMID 38282864, 2024). "In summary, our data may serve as a resource for future in vivo studies on GPR149 in the context of diet-induced obesity." (PMID 38282864, 2024).
cancer (1 paper, 2015). A tumor composed of atypical neoplastic, often pleomorphic cells that invade other tissues. "Six of fifty genes were not previously known to associate with cancer (HMGB1L5, LRRC58, GPR149, DZIP1L, C3orf77, and NUDT16)." (PMID 26491211, 2015).
metabolic disease (1 paper, 2024). A congenital disorder (due to inherited enzyme abnormality) or acquired (due to failure of a metabolically important organ) disorder resulting from an abnormal metabolic process. "Our current findings underscore the potential of GPR149 as a promising drug target for the treatment of metabolic diseases." (PMID 38282864, 2024).